CCL2 (C-C motif chemokine ligand 2)
Diseases named in the same sentence as CCL2 in open-access papers (continued):
Sharing a sentence is not in itself a finding about the gene and the disease.
HIV-1 infection (36 papers, 2008 to 2025). The type species of lentivirus and the etiologic agent of acquired immunodeficiency syndrome (AIDS). "Two single nucleotide polymorphisms (SNP) located in the CCL2 promotor region (-2136T) and in intron 1 (767G) are found strongly associated with an reduced susceptibility to human immunodeficiency virus 1 (HIV-1) infection." (PMID 33540898, 2021). "In contrast, CCL2 expression that is constitutively expressed at high levels in non-infected, cultured macrophages is further enhanced subsequent to HIV-1 infection of MDM but is generally suppressed in HIV-2-infected MDM." (PMID 38005838, 2023). "HIV-1 infection of human macrophages leads to the release of β-chemokines including CCL2, CCL3, CCL4, and CCL5." (PMID 38005838, 2023). "HIV-1 infection upregulates expression of both CCL2 and its receptor CCR2, and high levels of CCL2/CCR2 are observed in HIV-1-infected patients." (PMID 38005838, 2023). "For example, IL-1α, IL-10, CCL2, LMNA, and VCAM1, the target genes identified in this study, have been reported to be associated with HIV-1 infection and pathogenesis." (PMID 38110484, 2023). "In this respect, a recent study showed that CCL2, a chemokine induced upon HIV-1 infection, mobilizes Alix from F-actin to facilitate Gag-p6 mediated HIV-1 virion release." (PMID 36030822, 2022). "Macrophages are key targets of human immunodeficiency virus type 1 (HIV-1) infection and main producers of the proinflammatory chemokine CC chemokine ligand 2 (CCL2), whose expression is induced by HIV-1 both in vitro and in vivo." (PMID 33072075, 2020). "Our previous results demonstrated that HIV-1 infection leads to increased CCL2 expression, and here we report that CCL2 blocking strengthens the host immune response." (PMID 33072075, 2020). "CCL2 is a potent β-chemokine induced upon HIV-1 infection of primary human macrophages, as a host innate immune response designed to attract monocytes and T lymphocytes to trigger inflammation against the pathogen." (PMID 31172941, 2019). "We have previously found that CCL2 expression was up-regulated during monocyte differentiation to macrophages and it was further increased by HIV-1 infection; conversely, endogenously released CCL2 promoted HIV-1 replication." (PMID 25608886, 2015). "We previously found that CCL2 is up-regulated during monocyte differentiation to macrophages and it is further increased upon HIV-1 infection or exposure to viral proteins." (PMID 25608886, 2015). "CCL2 is a potent pro-inflammatory chemokine induced during HIV-1 infection and believed to be one of the key factors driving chronic inflammation and tissue damage in infected individuals." (PMID 25608886, 2015). "In the present study we have also investigated the expression of the chemokine CCL2/MCP-1, because it has been shown to be upregulated by HIV-1 infection both in vitro and in vivo with an overlapping pattern to that of the uPA/uPAR system." (PMID 23923008, 2013). "CCL2 is one of the most important pro-inflammatory products, secreted by immune-activated macrophages, which play a role in the pathogenesis of HIV-1 infection." (PMID 23555755, 2013). "The CCL2/CCR2 axis plays a critical role in the pathogenesis of HIV-1 infection." (PMID 38005838, 2023). "HIV-1 infection induced increased production of IP-10 and upregulated CCL2 secretion." (PMID 33298546, 2020). "Studies have also shown that CCL2 expression is significantly higher in the cerebrospinal fluid of HIV-1-infected individuals than that in healthy subjects, and the number of receptors with a high affinity for CCL2 is also significantly upregulated after HIV-1 infection." (PMID 32185196, 2020). "Furthermore, CCL2 drove monocyte infiltration into the brains of mice acutely infected with Theiler’s murine encephalomyelitis virus, and HIV-1 infection resulted in CCL2 mediated leukocytes across the BBB in a tissue culture model." (PMID 31664929, 2019).
HIV-1 infection (continued). "Therefore, we performed qPCR analysis for A3 family member transcripts in both control and anti-CCL2 Ab treated MDM at the time of HIV-1 infection (i.e., 20 h after treatment)." (PMID 25608886, 2015). "Therefore, we performed qPCR and Western blot analysis to evaluate SAMHD1 expression in both control and anti-CCL2 Ab treated MDM at the time of HIV-1 infection (i.e., 20 h after treatment)." (PMID 25608886, 2015). "Although the precise contribution of CCL2 in HIV-1 infection and pathogenesis remains to be established, growing evidence suggests that it may play important roles in these processes." (PMID 25608886, 2015). "Interestingly, enhanced CCL2 expression has been also found in ectocervical tissue explants following HIV-1 infection, and neutralization of the chemokine in this experimental system has been shown to result in viral transcription decrease." (PMID 25608886, 2015). "We observed a monocyte gene expression profile related to HIV-1 infection that indicated a “hybrid” monocyte with increased expression of macrophage-associated markers: monocyte chemotactic protein-1 (MCP-1, CCL2), CC-chemokine receptor 5 (CCR5), and sialoadhesin (Sn, CD169, Siglec 1)." (PMID 18414664, 2008). "We then investigated whether CCL2 blocking also inhibited a single cycle HIV-1 infection." (PMID 25608886, 2015). "Furthermore, an increase of CCL2 production following HIV-1 infection was found in these donors." (PMID 25608886, 2015). "In the Swiss HIV Cohort, we found that CXCL10, CCL2 and, to a lesser extent, CXCL9 transcripts were significantly upregulated during untreated HIV-1 infection." (PMID 37601355, 2023). "The HIV-1 infection of TZM-bl cells did have an effect; we observed decreased levels of IL-2 and CCL2 and increased levels of IL-6 and IL-8." (PMID 36432041, 2022). "CCL7, CCL2, CCL3 and others are overexpressed during HIV-1 infection, contributing to the secretion of more pro-inflammatory cytokines, leading to chronicity of the infectious process observed in HIV-positive individuals." (PMID 33557210, 2021). "Studies have shown that HIV-1 infection and immune-activated macrophages (HIV/MDM) secrete a range of neurotoxic substances, and CCL2 is an important component of HIV/MDM secretion." (PMID 32185196, 2020). "Another study showed that HIV-1 infection in primary human microglia induced the secretion of IL-6, IL-8, TNF-α, C-C Motif Chemokine Ligand 2 (CCL2), and Regulated upon Activation, Normal T cell Expressed and Secreted protein (RANTES)." (PMID 31614895, 2019). "The monocyte chemoattractant protein-1(MCP-1/CCL2) is also up-regulated in HIV-1 infected individuals; its plasma level correlates with virus (gp41) load in HIV-1 infection and expression level were diminished after antiviral therapy." (PMID 23383108, 2013). "Thus reduced CCL2-secretion might defavour HIV-1 infection of the vaginal mucosa in vivo." (PMID 21253014, 2011). "In addition, significant changes were observed in the expression of coding genes involved in the host response to infection (e.g., ISG15, STAT1, OAS3, ISG20, CCL2, and MX1), confirming robust HIV-1 infection of these cells." (PMID 31551335, 2019). "In addition to CCL2, other CC chemokines, namely CCL3, CCL4 and CCL5, are constitutively released by MDM and their production can be further increased following HIV-1 infection of these cells." (PMID 25608886, 2015). "In particular, CCL2, mainly produced by monocytes/macrophages both in vitro and in vivo, recruits CCR2+CD4+ T lymphocytes and monocytes/macrophages, which represent key target cells for HIV-1 infection." (PMID 25608886, 2015). "Interestingly, the levels of A3A expression elicited by CCL2 blocking in MDM are comparable to those of freshly isolated monocytes, where this enzyme has been demonstrated to restrict HIV-1 infection." (PMID 25608886, 2015).
HIV-1 infection (continued). "In contrast to these findings, and despite the bi-directional relationship between uPA and CCL2/MCP-1, HIV-1 infection of tonsil did not modulate the levels of soluble uPA and the number of uPA+ cells in the same tonsil histocultures." (PMID 23923008, 2013). "In addition, decreased CCL2 and CXCL7 expression may also contribute to the less pronounced activation of the immune system during HIV-2 infection compared to HIV-1 infection." (PMID 40507836, 2025). "Production of IL-12, IL-6, CCL-2, CXCL-10 and CXCL-12, that were also detected at day 14, was not significantly affected by either R5 or X4 HIV-1 infection (data not show)." (PMID 21767373, 2011). "Because CCL2 is not able to bind the HIV-1 coreceptors CCR5 and CXCR4, the authors suggested that carriers of those SNPs potentially exhibit an differential immune response to HIV-1 infection." (PMID 33540898, 2021).
osteosarcoma (36 papers, 2009 to 2025). A usually aggressive malignant bone-forming mesenchymal neoplasm, predominantly affecting adolescents and young adults. "The analysis of immunohistochemistry data and databases associated a positive correlation between CCL2 or MMP-3 levels with the metastasis of osteosarcoma patients." (PMID 37893141, 2023). "In addition, four macrophage-related prognostic genes (IL10, VAV1, CD14, and CCL2) had been identified, and the macrophage-related risk model had been validated to be reliable for evaluating prognosis in osteosarcoma." (PMID 34335756, 2021). "NF-κB functions as a key regulator of CCL2 expression, and its activation in osteosarcoma cells enhances the production of this chemokine, thus enhancing TAM recruitment." (PMID 39949765, 2025). "The screening of candidate targets in NGF-treated osteosarcomas revealed that the NGF-induced upregulation of VCAM-1 was more pronounced than that of ICAM-1 or CCL2." (PMID 39247831, 2024). "Records from the TCGA database and the Human Cancer Metastasis database revealed markedly elevated CCL2 expression levels in metastatic osteosarcoma samples, surpassing those in primary osteosarcoma samples." (PMID 37893141, 2023). "To confirm MMP-3’s involvement in osteosarcoma cell migration and invasion driven by CCL2, we treated osteosarcoma cells with an MMP-3 inhibitor or siRNA, both of which resulted in the inhibition of CCL2-induced enhancement of cell migration and invasion." (PMID 37893141, 2023). "Next, we directly employed the transwell assay, a well-established model for examining cell motility following CCL2 treatment in osteosarcoma cells." (PMID 37893141, 2023). "The TCGA database indicated that patients with higher stages (stage 3/4) of osteosarcoma exhibited significantly elevated levels of CCL2 expression compared to those observed in lower-stage patients (stage 1/2)." (PMID 37893141, 2023). "Our results revealed a robust increase in MMP3 mRNA expression after CCL2 stimulation in osteosarcoma cells compared to others." (PMID 37893141, 2023). "The results showed that 79 DEGs affected the prognosis of osteosarcoma, with PDE4C, CFAP44, CARNS1, GREB1L, ROF207 identified as significant risk factors and GBP1, MSC, GBP3, F13A1, CCL2 as substantial protective factors." (PMID 37796192, 2023). "We further investigated the impact of CCL2 on the migratory and invasive capacities of osteosarcoma cells in vitro and in vivo." (PMID 37893141, 2023). "Our findings underscore the correlation between heightened CCL2 levels and adverse outcomes, including cancer metastasis, in osteosarcoma." (PMID 37893141, 2023). "Our clinical data also found that CCL2 protein and mRNA expression levels in osteosarcoma patients were significantly higher than in normal individuals." (PMID 37893141, 2023). "CCL2 is an important chemokine that is reported to promote the proliferation and metastasis of osteosarcoma cells by activating NF-κB signaling." (PMID 37705968, 2023). "The stimulation of osteosarcoma cells with CCL2 enhanced migration and invasion abilities through the upregulation of MMP-3 synthesis." (PMID 37893141, 2023). "Monocyte chemotactic protein-1 (MCP-1)/CCL2, initially purified from monocytes and osteosarcoma cells, has both direct and indirect actions in cancer." (PMID 34503058, 2021). "Compared with the low-grade osteosarcoma, CCL2 expression was elevated in the osteosarcoma with high grade, which enhanced the proliferative and invasive abilities of osteosarcoma cells." (PMID 34335109, 2021). "Previous studies have shown that the CCL2 gene affects the proliferation of osteosarcoma cells through the RANKL signaling pathway." (PMID 33203792, 2020). "It has been reported that Bindarit, a specific inhibitor of CCL2, efficiently reduced the infiltration of macrophages and inhibited the growth of the osteosarcoma tumor." (PMID 33363016, 2020).
osteosarcoma (continued). "The cells from each of the treatment groups were implanted into mice to investigate the extent to which CCL2 affects the growth or invasion of cell-derived osteosarcoma tumors." (PMID 25695619, 2015). "The present study demonstrated that CCL2 promoted the proliferation and invasion of osteosarcoma cells." (PMID 25695619, 2015). "It was observed that the expression of CCL2 was higher in the more malignant osteosarcoma cell lines (LM8 and K7M3) compared with the less malignant cell lines (Dunn, K7 and K12)." (PMID 25695619, 2015). "Since the importance of chemokines in the occurrence and development of various types of cancer is increasing, it is important to investigate the role of CCL2 in the biology and pathophysiology of osteosarcoma." (PMID 25695619, 2015). "The present study performed RT-qPCR and western blot analysis to analyze the expression of CCL2 in the osteosarcoma cell lines." (PMID 25695619, 2015). "It was revealed that the high-grade osteosarcoma cells exhibited increased expression levels of CCL2 compared with the low-grade osteosarcoma cells (P<0.001)." (PMID 25695619, 2015). "Previous studies have demonstrated that CCL2 affects the proliferation of osteosarcoma cells via the RANKL signaling pathway." (PMID 25695619, 2015). "In osteosarcoma, crucial roles of CCL2 and its receptor CCR2 have been identified." (PMID 40109854, 2025). "The axis of CCL2/CCR2-mediated monocyte recruitment and polarization to M2-like TAMs has been causally linked to metastatic seeding in osteosarcoma models, a finding consistent with our inference of enhanced monocyte-to-macrophage differentiation within tumors." (PMID 41346635, 2025). "Compared to the sham group, the SNL group had higher gene expression levels of Gadd45g (growth arrest and DNA-damage-inducible 45 gamma) and Fos (FBJ osteosarcoma oncogene), while it had lower gene expression levels of Igf1, Ccl2, Hdac2, Rtn4rl1, Nfkb2, Gpr84, Pik3cg, and Abcc8." (PMID 38790607, 2024). "Thus, our findings suggest that MMP-3 is indeed involved in CCL2-induced osteosarcoma cell migration and invasion." (PMID 37893141, 2023). "Our findings revealed a concentration-dependent effect of CCL2 on osteosarcoma cell migration." (PMID 37893141, 2023). "Therefore, this study primarily focuses on investigating the ability of CCL2 to facilitate metastasis in osteosarcoma." (PMID 37893141, 2023). "The miR-3659 mimic significantly suppressed CCL2-promoted osteosarcoma migration and invasion." (PMID 37893141, 2023). "CCL2 also promotes osteosarcoma progression, metastasis, and bone resorption." (PMID 37025604, 2023). "We indicated that CCL2 promotes MMP-3-mediated migration of osteosarcoma." (PMID 37893141, 2023). "However, the effect of CCL2 on MMP regulation in the cell motility of osteosarcoma remains largely uninvestigated." (PMID 37893141, 2023). "Therefore, miR-3659 plays a crucial role in CCL2-induced osteosarcoma cell motility by regulating MMP-3 expression." (PMID 37893141, 2023). "In this study, we first examined the CCL2 levels in patients with osteosarcoma through an analysis of the TCGA database and the Human Cancer Metastasis Database and we confirmed the significant correlation between CCL2 expression and osteosarcoma stage, as well as distance metastasis." (PMID 37893141, 2023). "In addition, osteosarcoma cells attract normal bone marrow MSCs to the tumor stroma via secretion of CCL2, CXCL1 and TGF-β, supporting their trans-differentiation into cancer-associated fibroblasts (CAFs)." (PMID 34831167, 2021). "CCL2 expression is correlated with tumour prognosis in patients with osteosarcoma." (PMID 34464477, 2021). "In addition, the expression of CCL2 gene in high-grade osteosarcoma cells increased and promoted the proliferation and invasion of osteosarcoma cells." (PMID 33203792, 2020). "Furthermore, knockdown of CCL2 decreased the proliferation and invasion abilities of the osteosarcoma cells (P<0.01)." (PMID 25695619, 2015).